VHL (von Hippel-Lindau tumor suppressor)
Diseases named in the same sentence as VHL in open-access papers (continued):
Sharing a sentence is not in itself a finding about the gene and the disease.
oncocytoma (8 papers, 2005 to 2023). "Three of the patients identified with VHL mutations belonged to the ccRCC histotype, two were classified as angiomyolipomas, and one was described as oxyphilic adenoma." (PMID 37445575, 2023). "Anecdotal reports exist on VHL deletions in papillary carcinoma and clear cell (tubulo) papillary carcinoma as well as VHL mutations in individual cases of oncocytoma as well as chromophobe and papillary cancer." (PMID 32076485, 2020). "In total, the TMA contained n = 89 sporadic or VHL-associated ccRCC, n = 6 oncocytoma, n = 5 chrRCC and n = 2 sarcomatoid renal tumor samples that were included in the cilia frequency analysis." (PMID 23369289, 2013). "VHL mutation was also observed in a 72-year-old woman diagnosed with oncocytoma." (PMID 37445575, 2023). "One patient with VHL mutation represented angiomyolipoma and oncocytoma (oxyphilic adenoma)." (PMID 37445575, 2023). "However, individual cases of reported VHL mutations can be found also for these entities in the literature (1 of 6 oncocytomas, 2 of 7 chromophobe carcinomas)." (PMID 32076485, 2020). "In this study, we detected VHL mutations in all entities for which at least 10 cases could be successfully analyzed including 11 of 49 oncocytomas and in 7 of 38 chromophobe carcinomas." (PMID 32076485, 2020). "Case #20 contained the least amount of VHL positivity of 10%, while case #23 is a benign oncocytoma that is uniformly VHL-positive." (PMID 37069149, 2023). "Interestingly, VHL mutation was detected in two female patients diagnosed with AML and in one with oncocytoma." (PMID 37445575, 2023). "It is of note that most others have not found VHL mutations in chromophobe carcinoma and oncocytoma, which may be explained by the low numbers of analyzed cases (n = 2 – 17)." (PMID 32076485, 2020). "In contrast, VHL alterations did not exceed 30% in the other renal subtypes showing either small or no mutation/deletion overlap in oncocytoma (n = 43) or papillary renal cell carcinoma (n = 58), respectively, and a strikingly low mutation rate of approx. 10% in chromophobe renal cell carcinomas." (PMID 32076485, 2020). "Unlike VHL, BHD-associated RCC is associated with several different tumor histologies, with hybrid oncocytic (features of both chromophobe and oncocytoma) being the most prevalent, followed by chromophobe, oncocytoma, clear cell, and papillary subtypes." (PMID 33670168, 2021). "Interestingly, several cancer-related genes (VHL, HIF1A, cMET, phosphatase and tensin homolog, TSC1, BCL2, BRCA1), which include some tumor suppressors, were also found to be overexpressed in both the benign oncocytoma-like region and the high-grade oncocytic carcinoma region." (PMID 25275525, 2014).
osteosarcoma (8 papers, 2016 to 2024). A usually aggressive malignant bone-forming mesenchymal neoplasm, predominantly affecting adolescents and young adults. "Increased expression of miR-542-5p has not been previously reported in sporadic or VHL-associated ccRCC, but increased expression has been observed as a driver of osteosarcoma." (PMID 39062684, 2024). "Human osteosarcoma U2OS cell lines stably expressing non-targeting shRNA or shRNA against endogenous VHL were generated and 5MeC levels were measured using the same arrays." (PMID 29463811, 2018).
papillary renal cell carcinoma (8 papers, 2014 to 2025). A rare subtype of renal cell carcinoma, arising from the renal tubular epithelium and showing a papillary growth pattern, which typically manifests with hematuria, flank pain, palpable abdominal mass or nonspecific symptoms, such as fatigue, weight loss or fever. "This contrasted with a clear association between ascorbate content and the HIF pathway observed in papillary renal cell carcinomas with normal VHL and a functional hypoxic response." (PMID 30943919, 2019). "In papillary renal cell carcinoma, 3p deletions but not VHL mutations were significantly associated with both relapse-free survival and cancer specific death (p < 0.05, each)." (PMID 32076485, 2020). "Interestingly, mice with Vhl one-hit type 2B mutation develop renal cysts and fail to progress to renal adenocarcinoma, suggesting VHL mutation alone is not sufficient for transformation." (PMID 27682873, 2017).
Thrombocytopenia (8 papers, 2020 to 2025). A reduction in the number of circulating thrombocytes. "The VHL-based MA49 may also reduce the risk of thrombocytopenia and brain hemorrhage due to a very low expression of VHL in megakaryocytes." (PMID 39300221, 2024). "Notably, VHL levels are particularly low in platelets when compared to cancer cells, and therefore VHL-recruiting PROTACs could be advantageous in lowering the risk of patients developing thrombocytopenia." (PMID 37667522, 2023). "However, distinctly to Nav‐Gal, DT2216 has not been designed for targeting senescent cells, but for reducing thrombocytopenia (as platelets are characterized by poor VHL E3 ligase expression) while maintaining anti‐cancer properties." (PMID 32233024, 2020). "We have used the PROTAC technology to reduce navitoclax thrombocytopenia by converting it into a VHL E3 ligase targeted BCL-xL PROTAC, such as DT2216, because platelets are devoid of the VHL E3 ligase required for BCL-xL degradation." (PMID 38534371, 2024). "Since the VHL E3 ligase is poorly expressed in platelets, BCL-XL PROTACs targeted for degradation by that ligase did not induce thrombocytopenia, maintaining the same therapeutic efficacy as VHL that is expressed in the lymphomatous cells." (PMID 35249548, 2022). "Indeed, DT2216 specifically degrades BCLXL via VHL E3 ligase, without inducing thrombocytopenia." (PMID 37534243, 2023). "Since the VHL E3 ligase is poorly expressed in platelets, BCL-XL PROTACs targeted for degradation by that ligase do not induce thrombocytopenia, maintaining the same therapeutic efficacy as VHL is expressed in the lymphomatous cells." (PMID 32933565, 2020).
anemia (7 papers, 2016 to 2025). A reduction in the number of red blood cells, the amount of hemoglobin, and/or the volume of packed red blood cells. "In the VHL cohort, 95.5% of patients developed any-grade anemia with a median time to onset of 77 days (range 49-278)." (PMID 40920370, 2025). "Primary endpoint was safety; secondary endpoints included dose reduction, treatment interruption, treatment discontinuation, time to anemia onset, time to dose reduction, tumor shrinkage, objective response (per RECIST 1.1), and need for subsequent VHL-related procedures." (PMID 40937004, 2025). "We previously reported the design and characterization of VHL inhibitors VH032 and VH298 that block the VHL:HIF-α interaction, activate the HIF transcription factor, and induce a hypoxic response, which can be beneficial to treat anemia and mitochondrial diseases." (PMID 34174286, 2021).
Hyperglycemia (7 papers, 2019 to 2023). An increased concentration of glucose in the blood. "However, the underlying mechanisms facilitating PHD- and VHL-mediated HIF-1α degradation during hyperglycaemia are still not fully understood." (PMID 33496820, 2021). "This was further confirmed by similar results that were observed when HIF-1 activity was maintained during hyperglycemia in hypoxia by genetic approaches, that is silencing VHL that mediates HIF-1α degradation or overexpressing HIF-1α." (PMID 35164902, 2022). "The canonical oxygen-dependent regulation of HIF-1α is dependent on the hydroxylation of at least two critical prolines (Pro402/Pro564) that makes it accessible to VHL-dependent degradation, which is central for the effect of hyperglycemia on HIF." (PMID 31214621, 2019). "However, PHD inhibition or VHL inactivation can largely rescue HIF-1α stability, indicating an important role for PHD and VHL in mediating the degradation of HIF-1α during hyperglycaemia." (PMID 33496820, 2021). "Previous studies have shown that hyperglycemia destabilizes HIF-1α and impairs its function in diabetic mice through a VHL-dependent mechanism." (PMID 34099651, 2021). "Hyperglycaemia also induces the accumulation of methylglyoxal, which mediates HIF-1α destabilisation in a PHD- or VHL-independent manner." (PMID 33496820, 2021). "The aim of this study was to investigate the effect of the VHL protein inhibitor VH298 on wound healing, both in vitro and in a rat model with hyperglycaemia." (PMID 30911550, 2019). "Hyperglycemia disrupts HIF-1α stability and this disruption may be mediated by PHD or VHL, PHD inhibition or VHL inactivation can largely rescue HIF-1α stability, but the underlying mechanism is not fully understood." (PMID 37251664, 2023). "The effect of hyperglycemia on protein stability is dependent on VHL but not always restricted to the canonical proline hydroxylation." (PMID 31214621, 2019).
papillary thyroid carcinoma (7 papers, 2014 to 2026). "Our finding of VHL mutations in papillary carcinoma matches quite well with previous reports of smaller cohorts (3/28 and 2/30 cases)." (PMID 32076485, 2020). "Clear-cell and papillary carcinomas; VHL/HIF pathway alterations; characteristic metabolic reprogramming (glycolysis, lipid metabolism)." (PMID 41363728, 2026). "So far, just a few studies have investigated VHL in papillary thyroid cancer, and all reported it to be deregulated." (PMID 36036061, 2023). "The cohort of analyzed papillary carcinomas was also small in our study, but evidence for a possible prognostic role of 3p deletions but not of VHL mutations for both relapse-free survival and cancer specific death arises from this analysis." (PMID 32076485, 2020). "Alterations of the von Hippel–Lindau (VHL) tumor suppressor gene can cause different hereditary tumors associated with VHL syndrome, but the potential role of the VHL gene in papillary thyroid carcinoma (PTC) has not been characterized." (PMID 25490036, 2014). "Moreover, after normalized by VHL expression, MANF expression correlated with the OS and DFS of ccRCC patients, which was not seen in papillary carcinoma and chromophobe." (PMID 40603319, 2025).
triple-negative breast carcinoma (7 papers, 2015 to 2023). An invasive breast carcinoma which is negative for expression of estrogen receptor (ER), progesterone receptor (PR), and human epidermal growth factor receptor 2 (HER2). "Upregulation of miRNA-155 promoted tumor angiogenesis by targeting VHL and was associated with poor prognosis and triple-negative breast cancer." (PMID 26967247, 2016). "MiR-155 was found to accelerate tumor angiogenesis by directly suppressing von Hippel–Lindau (VHL) expression in triple-negative breast cancer." (PMID 30309377, 2018). "Here, we identify cyclin-dependent kinase 1 (CDK1) and peptidyl-prolyl cis-trans isomerase NIMA-interacting 1 (PIN1) as two previously uncharacterized regulators of pVHL in multiple types of human cancers harboring wild-type VHL including triple-negative breast cancer (TNBC)." (PMID 36813923, 2023).
tuberous sclerosis (7 papers, 2005 to 2025). Hereditary disease characterized by seizures, intellectual disability, developmental delay, and skin and ocular lesions. "Some of the most common hereditary syndromes associated with RCC include VHL, Birt–Hogg–Dube, and tuberous sclerosis." (PMID 38145031, 2023). "Tuberous sclerosis mutations activate mammalian target of rapamycin (mTOR) and biochemically resemble VHL alterations." (PMID 15956968, 2005). "Finally, in NEN associated with MEN2, NF1, VHL, and tuberous sclerosis data on the efficacy of SSAs are scarce and derive generally from case reports." (PMID 37581846, 2024). "This approach has previously proved successful, leading to the discovery of mizoribine and palbociclib as promising candidates for the treatment of tuberous sclerosis complex (TSC) and Von Hippel–Lindau (VHL)‐linked cancers, respectively." (PMID 39129390, 2025). "Although von Hippel–Lindau (VHL) mutations are predominant, RCC also develops in individuals with tuberous sclerosis (TSC)." (PMID 15956968, 2005).
lung adenocarcinoma (6 papers, 2017 to 2025). A carcinoma that arises from the lung and is characterized by the presence of malignant glandular epithelial cells. "This study provides evidence that GRK6 inhibition causes a decrease in VHL expression, leading to HIFα stabilisation with increased activity in lung adenocarcinoma, although the underlying mechanism merits further investigation." (PMID 34136390, 2021). "Among these were mutations in two well-known ccRCC cancer driver genes (VHL and PBRM1) and in EPHA4, a lung adenocarcinoma driver gene." (PMID 31212796, 2019). "The findings were further confirmed in lung adenocarcinoma samples, in which GRK6 expression levels negatively and positively correlate with HIF1α expression (P = 0.015) and VHL expression (P < 0.0001), respectively." (PMID 34136390, 2021). "This analysis identified von Hippel Landau (VHL) as one of the proteins from this cohort with the most significant inverse correlation score across this spectrum of malignancies, with lung adenocarcinoma and GBM demonstrating the strongest negative correlations between Daam2 and VHL." (PMID 29053101, 2017).
Parkinson disease (6 papers, 2008 to 2024). A progressive degenerative disorder of the central nervous system characterized by loss of dopamine producing neurons in the substantia nigra and the presence of Lewy bodies in the substantia nigra and locus coeruleus. "Well known examples are deregulation of the E3s BRCA1, Mdm2, VHL and Skp2 in various cancers, and Parkin in Parkinson's disease." (PMID 18213395, 2008). "Therefore, neural transplantation therapy for neurological diseases, such as Parkinson’s disease, using NSCs as donors is of great importance, with VHL expression potentially contributing to the understanding of these treatments." (PMID 36835292, 2023). "Previously, we demonstrated that SPKs differentiated into TH-positive neuron-like cells in vitro with intracellular delivery of VHL protein-derived peptide and that these transplanted cells functioned as dopaminergic neurons in the brain of Parkinson’s disease model rats." (PMID 29401731, 2018). "Furthermore, more than 50% of VHL transgenic NSCs transplanted into Parkinson’s disease rat models not only differentiated into tyrosine hydroxylase (TH)-positive dopamine-producing cells but also showed a marked reduction in apomorphine-induced turnover in behavioral analysis." (PMID 36835292, 2023).
renal oncocytoma (6 papers, 2005 to 2023). "Here, we investigate the cooccurrence of a pseudohypoxic condition with oncocytic transformation in a case of VHL-associated renal oncocytoma." (PMID 30728892, 2019). "Very few cases of renal oncocytoma occurring in the context of a VHL syndrome have been described, underlining the extremely low prevalence of this type of benign neoplasm when VHL is mutated." (PMID 30728892, 2019). "Genetic testing highlighted partial VHL gene deletion in a case study of a 63-year-old man with bilateral and multifocal renal oncocytoma." (PMID 37445575, 2023). "VHL protein expression was analyzed by immunohistochemistry (IHC) of large tissue sections of 25 ccRCC cases and one renal oncocytoma." (PMID 37069149, 2023). "Hence, we stained the renal oncocytoma for the hydroxylated form of HIF1α with the aim to understand whether the HIF1α positivity we observed was indeed due to the inactive form of the transcription factor, unable to be degraded in a VHL-deficient context." (PMID 30728892, 2019).
serous cystadenoma (6 papers, 2012 to 2025). A serous neoplasm in which the cysts and papillae are lined by a single layer of cells without atypia, architectural complexity or invasion. "For serous cystadenomas (SCAs), Von Hippel–Lindau (VHL) mutations seem more likely to be detected; VHL mutations associated with SCAs were assessed in four studies (1140 cysts)." (PMID 40507590, 2025). "On the other side of the shield, serous cystadenomas are related to von Hippel Lindau (VHL) syndrome, while mutations in the VHL gene are present in all SCAs in patients with VHL syndrome." (PMID 35299739, 2022). "Thus far, there are four known variants of serous cystadenoma, namely, macrocystic serous cystadenoma, solid serous adenoma, VHL-related SCN, and mixed serous neuroendocrine neoplasm, in which the serous epithelial components of these variants are identical to those of serous cystadenoma." (PMID 35299739, 2022). "In the context of VHL, the differential diagnoses of pNETs include serous cystadenoma or metastatic renal cancer lesions." (PMID 34025587, 2021). "The presence of mutation in VHL, with no other mutations, has 100% specificity for a serous cystadenoma." (PMID 33808853, 2021). "In a phase 2 trial, 53% of VHL pancreatic lesions responded to pazopanib (anti-VEGFR 1-3, anti-PDGFR α-β, c-KIT), but most of them were serous cystadenomas." (PMID 34025587, 2021).
vascular tumors (6 papers, 2009 to 2025). "RCC is a highly vascular tumor that can arise from abnormalities in the VHL gene and that leads to abnormal expression of angiogenesis-promoting growth factors such as vascular endothelial growth factor (VEGF)." (PMID 24251063, 2013). "Von Hippel-Lindau (VHL) disease is a hereditary condition caused by mutations in the VHL-tumor suppressor gene leading to constitutive overproduction of HIF-1alpha and HIF-2alpha, two proangiogenic factors, involved in the development of highly vascular tumors." (PMID 41024941, 2025).
viral infection (6 papers, 2017 to 2025). "Using VHL conditional knockout mice (Cd4-Cre) and acute virus infection or antigen immunization, the authors documented that VHL positively regulates Tfh cell development and function from the very initiation stages." (PMID 34943965, 2021). "However, overexpression of either human VHL(Δ61+R161W) mutant or BW-VHL via lenti-virus infection in 780-O cells under hypoxia enhanced expression of PAI-1and SOD2 significantly." (PMID 28178687, 2017). "Overexpression of human wild-type VHL via lenti-virus infection in 780-O cells under hypoxia had no obviously effect on expression of PAI-1 and SOD2, two well-defined HIF-2α down-stream genes." (PMID 28178687, 2017).
adrenal tumors (5 papers, 2017 to 2026). "Although, rare extra adrenal tumours can also be found in VHL, TMEM 127, NF1, and RET mutations as well." (PMID 29166454, 2017). "In 2006, a review from the European Network for the Study of Adrenal Tumors (ENS@T) summarized germline variants (VHL, SDHB, SDHD, RET, and NF1) in 166 (25.9%) of 642 PPGL patients and VHL was reportedly the most frequently mutated gene (56/642, 8.7%)." (PMID 33362715, 2020). "Considering the location of the tumour; intra-adrenal tumours suggest possible RET, VHL, NF1, TMEM 127, MAX or rarely KIF1B mutations." (PMID 29166454, 2017). "The patient’s presentation and subsequent genetic analysis underscore the importance of genetic testing in individuals with atypical presentations of adrenal tumors, even in the absence of a family history of VHL-associated conditions." (PMID 40051608, 2025).
hereditary tumor syndrome (5 papers, 2016 to 2021). "Approximately 25–30% of these tumors develop under conditions of a hereditary tumor syndrome a third of which are caused by mutations in the Von Hippel Lindau (VHL) gene." (PMID 28187001, 2017). "Patients affected by hereditary tumor syndromes, such as VHL and TSC, undergo periodical Gd MRI screening, according to international guidelines." (PMID 29312473, 2018). "Therefore, only the specific phenotypes may guide the clinician in choosing the most accurate genetic test, but the successive testing of genes related to the well-known hereditary tumor syndromes (MEN2, VHL, NF1 and paraganglioma syndromes) would lead to a long and burdensome process." (PMID 34439371, 2021).